SELENOP (selenoprotein P)
Diseases named in the same sentence as SELENOP in open-access papers (continued):
Sharing a sentence is not in itself a finding about the gene and the disease.
Anxiety (4 papers, 2006 to 2026). Intense feelings of nervousness, tension, or panic often arise in response to interpersonal stresses. "A significant association was found between selenoprotein P and symptoms of depression (p = 0.006), as well as between selenoprotein P and symptoms of anxiety (p = 0.012)." (PMID 39858985, 2024). "Thus, the results are not representative of the overall population, and further repetition with greater samples is mandated before recognizing selenoprotein P as a valid predictor of the pathogenic mechanism underlying symptoms of depression and anxiety." (PMID 39858985, 2024). "The Pearson chi-square test was used for the association between levels of selenoprotein P and the PHQ-9 score (symptoms of depression) and GAD-7 score (symptoms of anxiety), which were divided into study and control groups accordingly." (PMID 39858985, 2024). "As selenium and selenoprotein P are repeatedly shown to interact and correlate with each other and further correlate with symptoms of depression and anxiety, it is important to continue exploring these pathways further." (PMID 39858985, 2024). "Further research opportunities may exist in yet-unrecognized oxidative stress mechanisms involving selenium and selenoprotein P pathways in the development of different disorders, such as depression and anxiety." (PMID 39858985, 2024). "This study aimed to determine whether lower selenium and selenoprotein P levels correlate with high levels of depression and anxiety symptoms." (PMID 39858985, 2024). "The possible correlations between selenium and selenoprotein P with the symptoms of depression and anxiety illustrate the potential of further studies with bigger sample sizes to study the potential relationship between selenium levels and mental health outcomes to a greater extent." (PMID 39858985, 2024). "However, alternative unrecognized oxidative stress mechanisms involved in the development of symptoms of depression and anxiety, involving selenium and selenoprotein P pathways, may exist." (PMID 39858985, 2024). "Consequently, we aimed to further explore the link between oxidative stress mechanisms and mental health, by assessing whether blood plasma levels of selenium and selenoprotein P correlate with symptoms of depression and anxiety in employed, fourth-year working medical students." (PMID 39858985, 2024). "However, there is no conclusive evidence about the relevance of selenium and selenoprotein P levels in relation to symptoms of depression and anxiety." (PMID 39858985, 2024).
autoimmune disease (4 papers, 2021 to 2023). A disorder resulting from loss of function or tissue destruction of an organ or multiple organs, arising from humoral or cellular immune responses of the individual to their own tissue constituents. "SELENOP protein is a transport carrier for the essential trace element selenium, which is mainly expressed in the liver and secreted into the plasma and has been shown to be associated with autoimmune diseases." (PMID 37654485, 2023). "SELENOP is a biomarker of selenium status that has been identified as a major preventable trigger for autoimmune diseases including RA." (PMID 35330214, 2022). "Notably, certain genotypes associate with autoimmune disease (AID) risk and autoantibody titers, e.g., in selenoprotein S (SELENOS) or selenoprotein P (SELENOP)." (PMID 34445238, 2021).
liver cancer (4 papers, 2020 to 2024). An epithelial or non-epithelial malignant neoplasm that arises from the liver. "These insights may lead to better diagnostic tools and personalized treatments for liver cancer, emphasizing the need for further studies to validate selenoprotein P’s clinical utility in real-world settings." (PMID 39001444, 2024). "Furthermore, the investigation aims to unravel the intricate connections between SELENOP and hormonal/metabolic biomarkers, shedding light on the molecular mechanisms underlying SELENOP’s involvement in liver cancer for the development of novel diagnostic and therapeutic strategies." (PMID 39001444, 2024). "This attests to our model’s high efficacy in capturing and explaining the observed patterns in SELENOP mRNA expression within the context of liver cancer." (PMID 39001444, 2024). "This research explores the role of selenoprotein P, a protein crucial for transporting selenium in the body, in liver cancer." (PMID 39001444, 2024). "Robust positive correlations are evident with key hormonal markers such as AR (ρ = 0.668), ESR1 (ρ = 0.547), and THRB (ρ = 0.424), underscoring the intricate involvement of SELENOP in hormonal pathways within the realm of liver cancer." (PMID 39001444, 2024). "Despite its established role in selenium metabolism, the specific functions of SELENOP in the development of liver cancer remain enigmatic." (PMID 39001444, 2024). "The identified connections with key lipid/triglyceride metabolism biomarkers, namely PPARA, APOC3, and APOA5, suggest the involvement of SELENOP in lipid homeostasis within the context of liver cancer." (PMID 39001444, 2024). "The literature has shown that an increase in serum Se leads to an increase in the expression of selenoprotein P, and the inhibition of proinflammatory factors and its content in liver cancer cells is significantly reduced compared to healthy ones." (PMID 37628834, 2023). "Furthermore, the subsequent robust regression model not only corroborates these intricate correlations but accentuates the substantial impact of both hormonal and lipid metabolic factors on SELENOP mRNA expression in the context of liver cancer." (PMID 39001444, 2024). "In future, investigating SELENOP’s dynamic interactions with hormonal and lipid/triglyceride metabolism biomarkers is vital for nuanced comprehension of its mechanistic involvement in liver cancer." (PMID 39001444, 2024). "In general, this study aims to comprehensively investigate SELENOP’s diverse roles in liver cancer, guided by the rationale that its multifaceted functions warrant exploration using machine learning approaches for the discovery of novel biomarkers in HCC translational medicine." (PMID 39001444, 2024).
lung carcinoma (4 papers, 2015 to 2025). "The C-type lectin domain family 3 member B (CLEC3B), membrane primary amine oxidase (AOC3), hemoglobin subunit beta (HBB), catalase (CAT), and selenoprotein P (SEPP1) were screened as candidate protein markers for early-stage lung cancer." (PMID 40496615, 2025).
Parkinson disease (4 papers, 2021 to 2025). A progressive degenerative disorder of the central nervous system characterized by loss of dopamine producing neurons in the substantia nigra and the presence of Lewy bodies in the substantia nigra and locus coeruleus. "SELENOP changes in the substantia nigra (SN) and the vagus nucleus in Parkinson’s disease showed that SELENOP plays a role in the dopaminergic transmission of SN neurons and the black striatum, and it may be important for the survival of these neurons in PD." (PMID 34769138, 2021). "SELENOS levels in PD are directly affected by changes in SELENOP levels, and SELENOS contributes to changing the levels of aggregated proteins, though its exact role in Parkinson’s disease remains unclear." (PMID 39941073, 2025).
pulmonary arterial hypertension (4 papers, 2020 to 2021). Pulmonary arterial hypertension (PAH) is a group of diseases characterized by mean pulmonary artery pressure >20 mmHg and elevated pulmonary arterial resistance leading to right heart failure. "Recently, elevated SELENOP levels have been suggested as diagnostic marker and therapeutic target in pulmonary arterial hypertension (PAH)." (PMID 32630589, 2020). "A recent study has reported that the up-regulation of SELENOP is related to an increase in insulin resistance and exercise resistance, a decrease in insulin secretion and the proliferation of smooth muscle cells in pulmonary hypertension." (PMID 34142161, 2021). "Details are not fully elucidated, but the role of ApoER2 as a mediator of signal transduction has been known, which is realized by pulmonary arterial hypertension (PAH) where the increased expression of SELENOP in pulmonary artery smooth muscle cells (PASMCs) forms lesions." (PMID 34124127, 2021).
Stroke (4 papers, 2019 to 2025). Sudden impairment of blood flow to a part of the brain due to occlusion or rupture of an artery to the brain. "Impaired selenoprotein P function adversely affects selenium homeostasis, attenuating its cytoprotective effects and consequently increasing susceptibility to stroke." (PMID 41426996, 2025). "When breaking up cardiovascular events into its two components, subjects with SELENOP deficiency were at significantly increased risk of both coronary artery disease (490 events) [1.27 (1.03–1.57) (p = 0.025)] and stroke (305 events) [1.57 (1.21–2.02) (p = 0.001)]." (PMID 31404994, 2019).
amyotrophic lateral sclerosis (3 papers, 2022 to 2023). Amyotrophic lateral sclerosis (ALS) is a neurodegenerative disease characterized by progressive muscular paralysis reflecting degeneration of motor neurons in the primary motor cortex, corticospinal tracts, brainstem and spinal cord. "In addition, low CSF concentrations of selenoprotein P-bound selenium have been associated with increased risk of amyotrophic lateral sclerosis, a sporadic adulthood onset motor neuron disorder." (PMID 37543540, 2023).
atherosclerosis (3 papers, 2018 to 2020). A disease characterized by the build-up of fatty material and calcium deposition in the arterial wall resulting in partial or complete occlusion of the arterial lumen. "In addition, the administration of purified SELENOP was suggested to impair insulin signaling and disturb glucose metabolism, as well as play a role in the development of atherosclerosis." (PMID 32377302, 2020).
colorectal adenoma (3 papers, 2015 to 2018). An adenoma that arises from the colon or rectum. "Furthermore, studies of single nucleotide polymorphisms revealed an association of both TR1 and selenoprotein P (SEPP1) with advanced colorectal adenomas in humans." (PMID 25886253, 2015).
Crohn disease (3 papers, 2013 to 2024). A gastrointestinal disorder characterized by chronic inflammation involving all layers of the intestinal wall, noncaseating granulomas affecting the intestinal wall and regional lymph nodes, and transmural fibrosis. "Patients with IBD show a decrease in SEPP1 (exhibits reductase and peroxidase activity) and SELENOP, especially in patients with Crohn’s disease." (PMID 38673974, 2024). "There is a decrease in selenoprotein P (SEPP1) in the serum, as well as decrease in the activity of glutathione peroxidase in Crohn’s Disease patients." (PMID 29494512, 2018). "Serum selenoprotein P (Sepp1) levels are significantly lower in patients with Crohn’s disease and glutathione peroxidase 1 mRNA is significantly downregulated in mononuclear cells from patients with IBD." (PMID 23861820, 2013).
dementia (3 papers, 2022 to 2025). Loss of intellectual abilities interfering with an individual's social and occupational functions. "In this first prospective study of circulating (blood and CSF) concentrations of selenoprotein P and dementia risk, greater concentrations were generally predictive of higher risk, particularly when exposure assessment was based on the full-length protein assay AA3." (PMID 37258587, 2023). "This suggests that the occurrence of cognitive impairment and particularly of dementia is associated with alterations of selenoprotein P concentrations, which could be either a consequence of or a risk factor for these conditions." (PMID 36077261, 2022). "The predictive effects of high circulating concentrations of selenoprotein P in blood and to a lower extent in CSF may indicate either a predictive role of this selenium-containing protein for conversion to dementia or a direct causal role in the progression to the disease from MCI." (PMID 37258587, 2023). "Another study reported that elevated selenoprotein P levels in serum and cerebrospinal fluid were associated with an increased risk of MCI conversion to dementia." (PMID 39940451, 2025). "Overall, our findings suggest that dementia should also be considered when dealing with the adverse effects of selenoprotein P, in addition to metabolic and vascular endpoints ascribed to selenoprotein P excess." (PMID 37258587, 2023). "Risk ratios of dementia peaked at 2–6 at the highest levels of selenoprotein P, when compared to its median level, also depending on matrix, analytical methodology and dementia subtype." (PMID 37258587, 2023). "If not due to unmeasured confounding, our results indicate a possible adverse effect of high concentrations of selenoprotein P in dementia etiology, in line with deleterious effects recently ascribed to selenoprotein P with reference to metabolic disease risk." (PMID 37258587, 2023). "Using sandwich ELISA methods, we measured full-length selenoprotein P concentrations in serum and cerebrospinal fluid to assess the relation with dementia incidence during a median follow-up of 47.3 months." (PMID 37258587, 2023). "In conclusion, results from this first in vivo prospective cohort study, suggest that concentrations of two biomarkers of full-length selenoprotein P levels in serum and CSF predict conversion towards dementia among individuals with MCI." (PMID 37258587, 2023). "In particular, there is a need for prospective studies in humans to assess the role of selenoprotein P in dementia etiology, possibly assessing its concentrations in the central nervous system through its cerebrospinal fluid content and encompassing a satisfactorily longer period of follow-up." (PMID 37258587, 2023). "In this cohort study, we ascertained baseline biomarkers of selenoprotein P in cerebrospinal fluid and blood of subjects with mild cognitive impairment (MCI) and assessed the extent to which these biomarkers were related to subsequent progression to dementia." (PMID 37258587, 2023).
glioblastoma (3 papers, 2022 to 2025). The most malignant astrocytic tumor (WHO grade IV). "In glioblastoma (GBM), SELENOP maintains GPx1 and GPx4 levels, contributing to ferroptosis sensitivity and offering a potential target for overcoming drug resistance." (PMID 39942544, 2025).
Hashimoto thyroiditis (3 papers, 2017 to 2023). An autoimmune disorder caused by the production of autoantibodies against thyroid tissue. "Recently, autoantibodies to the Se transporter SELENOP (SELENOP-aAb) have been identified in Hashimoto's thyroiditis and shown to impair selenoprotein expression." (PMID 37423160, 2023). "Using a newly established quantitative immunoassay, SELENOP autoantibodies were particularly prevalent in Hashimoto’s thyroiditis as compared with healthy control subjects (6.6% versus 0.3%)." (PMID 34884891, 2021). "Among the patients, elevated SELENOP-aAb was mainly found in patients with Hashimoto’s thyroiditis." (PMID 34884891, 2021). "We investigated Se serum and selenoprotein P (SePP) levels in Graves’ disease (GD) with and without GO, Hashimoto's thyroiditis (HT) patients and in 27 control individuals (C)." (PMID 29412385, 2017).
lipid metabolism disorders (3 papers, 2024 to 2025). "Furthermore, meta-analyses have confirmed the association between high circulating levels of SELENOP and various glucose and lipid metabolism disorders." (PMID 39149550, 2024). "Elevated circulating levels of SELENOP have been observed in obese individuals, and a deficiency in Selenof, Selenom, Selenos, Selenot, or Selenov has been shown to lead to lipid metabolic disorder in established mouse models and usually exacerbates HFD-induced lipid accumulation in the body." (PMID 39339808, 2024).
mild cognitive impairment (3 papers, 2015 to 2023). "In this case–control study, we determined selenoprotein P concentrations in both the cerebrospinal fluid (CSF) and the serum of 50 individuals diagnosed with ALS, 30 with AD, 54 with mild cognitive impairment (MCI) and of 30 controls, using sandwich enzyme-linked immunosorbent assay (ELISA) methods." (PMID 36077261, 2022).
non-alcoholic fatty liver disease (3 papers, 2020 to 2021). "Cirrhotic or fibrotic liver tissue causes reduced serum Se concentrations, and a recent report indicated a gradual decrease of serum SELENOP concentrations in non-alcoholic fatty liver disease (NAFLD) and steatohepatitis (NASH)." (PMID 33672988, 2021).
sarcopenia (3 papers, 2020 to 2025). Progressive decline in muscle mass due to aging which results in decreased functional capacity of muscles. "It was upregulated in sarcopenia models and served as a ‘sponge’ for miR‐181a to promote SEPP1 (selenoprotein P) expression, thereby inhibiting muscle differentiation and regeneration." (PMID 40034097, 2025).
chronic fatigue syndrome (2 papers, 2023). "•Autoantibodies to SELENOP are relatively frequent in chronic fatigue syndrome." (PMID 37423160, 2023). "In a recent trial, selenium biomarkers, such as plasma selenium, glutathione peroxidase, and selenoprotein P, showed linear correlations in patients with chronic fatigue syndrome without reaching saturation, indicative of Se deficiency." (PMID 37686861, 2023).
chronic hepatitis C (2 papers, 2019 to 2021). "We observed that hepatic expression of SELENOP significantly declines in the pre-cirrhotic/cirrhotic (F3/4) liver than in the F1/2 liver in patients with chronic hepatitis C." (PMID 33693023, 2021).
Cirrhosis (2 papers, 2022 to 2024). A chronic disorder of the liver in which liver tissue becomes scarred and is partially replaced by regenerative nodules and fibrotic tissue resulting in loss of liver function. "Furthermore, lower circulating SELENOP levels and hepatic mRNA SELENOP expression were observed in patients with cirrhosis." (PMID 39001444, 2024).
endometrial cancer (2 papers, 2022 to 2025). Primary or metastatic malignant neoplasm involving the endometrium (mucous membrane that lines the endometrial cavity). "The HPA database provided IHC images of endometrial cancer and normal endometrial tissues, allowing us to confirm the differential expression of CDKN2A, SELENOP, GSN, PGR, and TRPC1 at the protein level." (PMID 41244925, 2025). "IHC images revealed that CDKN2A, SELENOP, and TRPC1 were expressed at higher levels in endometrial carcinoma tissues compared to normal endometrial tissues, consistent with their mRNA upregulation in high-risk patients." (PMID 41244925, 2025).
epilepsy (2 papers, 2022 to 2024). A brain disorder characterized by episodes of abnormally increased neuronal discharge resulting in transient episodes of sensory or motor neurological dysfunction, or psychic dysfunction. "Consequently, we hypothesized that Se and SELENOP deficiencies are prevalent in children with impaired neurodevelopment, and that low Se status constitutes a particularly frequent finding in paediatric patients with epilepsy, especially in a European country with borderline Se supply like Germany." (PMID 35745104, 2022). "Some more interesting findings were noted when testing additional hypotheses related to other TE and paediatric diseases, i.e., a relatively elevated Cu and Zn status in children with epilepsy, and a general trend towards low Se, SELENOP, and GPX3 levels in phacomatoses were noted." (PMID 35745104, 2022).
gestational diabetes (2 papers, 2018 to 2024). Carbohydrate intolerance first diagnosed during pregnancy. "Recently, a study from the Odense Child Cohort suggested an association between lower serum selenium and selenoprotein P levels during pregnancy, which were significantly linked to gestational diabetes." (PMID 38888992, 2024).
liver cirrhosis (2 papers, 2020 to 2022). "Despite a net drop in serum selenium and Selenoprotein P concentration in both groups, glutathione peroxidase activity increased in patients with liver cirrhosis." (PMID 36079882, 2022).